C1D (C1D nuclear receptor corepressor)
Description:
Plays a role in the recruitment of the RNA exosome complex to pre-rRNA to mediate the 3'-5' end processing of the 5.8S rRNA; this function may include MPHOSPH6. Can activate PRKDC not only in the presence of linear DNA but also in the presence of supercoiled DNA. May regulate the TRAX/TSN complex formation. Potentiates transcriptional repression by NR1D1 and THRB (By similarity).
Synonyms: hC1D; SUNCOR; SUN-CoR; LRP1; Rrp47
Tractability: PROTAC: UniProt records ubiquitination sites on it; ubiquitination databases record sites on it; its protein half-life has been measured.
Gene: Protein-coding gene on chromosome 2 (68,041,130 to 68,110,948, reverse strand). Ensembl gene ENSG00000197223.
Subcellular location: Nucleus; Cytoplasm; Nucleus, nucleolus
Subcellular location (Human Protein Atlas): Nucleoli; Nucleoplasm
Pathways (Reactome):
Metabolism of RNA: Major pathway of rRNA processing in the nucleolus and cytosol; Nuclear RNA decay
Gene Ontology:
Molecular function: protein binding; RNA binding; DNA binding; nuclear receptor binding; transcription corepressor activity
Biological process: maturation of 5.8S rRNA; regulation of gene expression; negative regulation of DNA-templated transcription
Cellular component: cytoplasm; nucleolus; nucleoplasm; nucleus; exosome (RNase complex); nuclear exosome (RNase complex); transcription repressor complex
Genetic constraint (gnomAD): Loss-of-function variants: 2 observed, 7.62 expected, observed/expected ratio (o/e) 0.26, 90% interval 0.11 to 0.83. That is too few expected variants to judge how well the gene tolerates losing a copy. Missense variants: 102 observed, 108.77 expected, observed/expected ratio (o/e) 0.94, 90% interval 0.8 to 1.11. Synonymous variants: 38 observed, 35.71 expected, observed/expected ratio (o/e) 1.06, 90% interval 0.82 to 1.39.
Homologues: Orthologues: macaque C1D (99% identical), pig C1D (97% identical), dog C1D (96% identical), rat C1d (91% identical), mouse C1d (90% identical), tropical clawed frog c1d (71% identical), zebrafish c1d (59% identical), Caenorhabditis elegans Y51H7C.7 (26% identical).
Diseases named in the same sentence as C1D in open-access papers:
C1D is named in the same sentence as 16 diseases in open-access papers, as found by Europe PMC text mining. Sharing a sentence is not in itself a finding about the gene and the disease. The quoted sentences say what the papers report.
breast carcinoma (2 papers, 2017 to 2022). "When murine breast cancer 4T1 cells, including 4T1-Luc, 4T1-Luc-c1d and 4T1-Luc-c5d, were exposed to HA for indicated times, ERK relocated to the nucleus in 10-20 min." (PMID 27845895, 2017). "After quantitative calculation, the levels of serum CCL18 and CXCL1 antigens, and C1D, TM4SF1, FXR1, and ZNF573 IgG autoantibodies were significantly higher in patients with OC than in those with cervical cancer, liver cancer, breast cancer, gynecological benign tumor patients, and healthy women." (PMID 34995016, 2022).
endothelial dysfunction (1 paper, 2025). In vascular diseases, endothelial dysfunction is a systemic pathological state of the endothelium (the inner lining of blood vessels) and can be broadly defined as an imbalance between vasodilating and vasoconstricting substances produced by (or acting on) the endothelium. "The identification of C1D as a functional partner of Gm39822 provides new insights into endothelial dysfunction, emphasizing the importance of lncRNA-mediated transcriptional regulation in vascular biology." (PMID 40943070, 2025).
xeroderma pigmentosum (1 paper, 2016). Xeroderma pigmentosum (XP) is a rare genodermatosis characterized by extreme sensitivity to ultraviolet (UV)-induced changes in the skin and eyes, and multiple skin cancers. "C1D has also been implicated in DNA damage repair following UV radiation, with C1D expression dependent on xeroderma pigmentosum B (XPB), an important component of the nucleotide excision repair (NER) pathway." (PMID 27030795, 2016).
cancer (4 papers, 2011 to 2025). A tumor composed of atypical neoplastic, often pleomorphic cells that invade other tissues. "Moreover, other genes upregulated in distinct but also specific stimuli like PPA1, GADD45B, C1D, TRPV2 and RPS14 were associated with DDR, cancer and apoptosis." (PMID 39623312, 2024). "In summary, combined detection of CCL18 and CXCL1 chemokines, and C1D, TM4SF1, FXR1, and ZNF573 autoantibodies can improve the specificity and sensitivity of OC diagnosis, and its diagnostic efficiency is higher than that of other malignant tumors." (PMID 34995016, 2022).
tumor (3 papers, 2013 to 2025). "In this vein, overexpression of C1D in human tumor cell lines has been shown to cause an increased incidence of apoptosis." (PMID 23580640, 2013). "Overall, inhibition of the proteasome-mediated degradation of C1D, together with the ability to control its transcription in tumor cells, may be concomitantly utilized for the treatment of tumor cells." (PMID 27030795, 2016). "Controlling the transcription of C1D could therefore offer a significant step forward in gene therapy for apoptosis induction in tumor cells." (PMID 27030795, 2016). "Indeed, C1D overexpression in tumor cells induces their apoptosis." (PMID 27030795, 2016).
cardiovascular disorder (1 paper, 2025). A disease involving the cardiovascular system. "Future studies will be required to further elucidate the role of C1D in cardiovascular disease models." (PMID 40943070, 2025).
C1D also shares sentences with these, for which no sentence is quoted: atherosclerosis (1 paper); autoimmune disease (1); cervical cancer (1); gynecological benign tumor (1); infection (1); liver cancer (1); lupus (1); meningioma (1); multiple myeloma (1); ovarian carcinoma (1).